COL1A1 (collagen type I alpha 1 chain)
Diseases named in the same sentence as COL1A1 in open-access papers (continued):
Sharing a sentence is not in itself a finding about the gene and the disease.
tumor (continued). "More accurately, tumor stroma might play an important role in negative immunoregulation since the hub genes (i.e., CTHRC1, COL1A1, LOXL2, P4HA3, and FKBP10) related to immunosuppressive GO terms usually participate in collagen formation." (PMID 33791227, 2021). "Indeed, as examples, the high expressions of fibroblasts, myofibroblast markers (COL1A1, COL1A2), and B cell markers (IGLC3, IGHG3) were found in our LMD-isolated stroma samples and TCGA tumor samples, but not in our LMD-isolated tumor parts." (PMID 33916417, 2021). "Apart from confirming targets, such as ERBB2 and S100A11, which are exclusively upregulated in the tumour epithelial cells, qPCR data confirmed that stromal targets such as SPARC, TIMP1, IGFBP7, COL1A1 were upregulated specifically in stromal components and not in epithelial components." (PMID 31959771, 2020). "Gene expression analysis of paired tumor-non-tumor samples from TCGA-LIHC cohort (n = 438) also showed 1.13-(p < 0.001), 1.01-(p < 0.01), and 1.07-(p < 0.001) fold reduction in COL1A1, COL1A2 and COL4A1 mRNA expression in the HCC tumor compared to the non-tumor ‘normal’ liver samples." (PMID 31181620, 2019). "There was no inter-tumour correlation of the TAM’s expression of FAP and tumoral Col1a1 expression." (PMID 30054470, 2018).
cancer (368 papers, 2007 to 2026). A tumor composed of atypical neoplastic, often pleomorphic cells that invade other tissues. "COL1A1 is typically overexpressed in numerous cancers, where it is often associated with aggressive disease and poor prognosis." (PMID 41469472, 2025). "COL1A1+ stromal cells were categorized into four major clusters: cancer-associated fibroblasts (fib), identified by high expression of PDGFRA, were further divided into four subgroups." (PMID 41281745, 2025). "By using markers of specific clusters, we identified five distinct cell types, including cancer‐associated fibroblasts (CAFs) (COL1A1), endothelial cells (PECAM1), epithelial cells (CDH1), immune cells (PTPRC), and neurons (RELN)." (PMID 40038875, 2025). "Cancer-associated fibroblasts (CAFs), marked by Col1a1, Cdh2, Epha6, and Prkch, were classified into two subtypes (CAFs 1 and 2)." (PMID 40723284, 2025). "Module III is enriched with genes of cancer-associated fibroblasts (CAFs) like COL1A1, COL1A2, and COL3A1, distributing spatially around cancer cells for tumorigenesis promotion." (PMID 40033360, 2025). "We identified a population of cancer-associated fibroblasts (CAFs), marked by the expression of genes such as COL1A1, COL3A1, COL11A1, and ACTA2, which are known to contribute to the activation of EMT programing." (PMID 40950184, 2025). "In mice with PDAC caused by spontaneous mutations, deletion of Col1A1 from a-SMA positive myofibroblasts increased cancer progression." (PMID 40677714, 2025). "COL1A1 is the main constituent of type I collagen, and abnormal COL1A1 expression is associated with many cancers." (PMID 38605343, 2024). "Based on recent advancements in cancer genetics, COL1A1-PDGFB gene mutations have been revealed in DFSP." (PMID 39727629, 2024). "COL1A1, which encodes collagen type I alpha 1 chain, has been implicated in promoting metastasis in various cancers." (PMID 39065771, 2024). "Dysregulation of COL1A1 has been implicated in tumorigenesis and cancer progression in multiple malignancies." (PMID 38913913, 2024). "COL1A1 is highly expressed in a variety of cancers and regulates cellular processes, and high COL1A1 expression is also associated with poor cancer prognosis." (PMID 38979664, 2024). "COL1A1 was found to be one of the cancer-associated fibroblast (CAF) markers for GC and a poor prognostic signature gene for CAF infiltration." (PMID 38903804, 2024). "The two matrix CAF (cancer associated fibroblast) subclusters, C4, and C7, exhibited high expression of COL1A1." (PMID 38010945, 2024). "Regarding carcinoma‐associated fibroblasts, several subsets expressing COL1A1 were enriched in dHGP, while αSMAlow_single cells were present at higher densities in non‐dHGP." (PMID 39563958, 2024). "Cancer associated fibroblast cells were identified through the classic Maker gene (Mmp2, Apod, Dcn, and Col1a1) in all cells." (PMID 36382024, 2022). "In summary, the high expression of COL1A1 is associated with poor prognosis of various cancers and higher levels of immune infiltration, especially in LGG." (PMID 35789341, 2022). "This is consistent with augmented Col1a1 expression in cancer cells that associates with high rates of metastasis and poor survival." (PMID 36547361, 2022). "Both lncRNAs and COL1A1 are associated with the regulation of miRNA expression or PI3K/AKT signaling pathway activity in cancer." (PMID 35842617, 2022). "Another study on COL1A1 showed that regulation of the PI3K-AKT signaling pathway in cancer was associated with higher COL1A1 expression levels." (PMID 35842617, 2022). "Based on the TCGA-LUSC cohort, a high percentage of cancer associated fibroblasts and COL1A1, COL3A1, POSTN1 and TIMP3 expression was also associated with resistance to immunotherapy." (PMID 35480306, 2022). "As for KEGG pathways, COL1A1 was associated with microRNAs in cancer, PI3K-Akt signaling pathway, and regulation of actin cytoskeleton." (PMID 33490271, 2021).
cancer (continued). "High expression of COL1A1 has been shown to be closely linked to the progression of various cancers." (PMID 33490271, 2021). "This revealed young and aged patients with primary cancers expressing high levels of COL1A1 are at greater risk of death and have shorter PFS." (PMID 33980846, 2021). "Among these host genes, hsa_circ_0044520 and hsa_circ_0044529 are hosted in the collagen type I alpha 1 chain (COL1A1) gene, which can encode the subunit of type I collagen and regulate the tumourigenesis of various cancers." (PMID 31937318, 2020). "For the data set of OV, 67 genes were identified by univariate Cox regression to be significantly associated with the cancer and seven of them, namely COL1A1, COL3A1, RPL10, ARHGAP5, LATS1, TSHR and SLC34A2, were found in the CGC data set." (PMID 32429941, 2020). "These bioinformatics-based statistical data do indicate a strong association between COL1A1, markers of metastasis and cancer stemness, as well as suggest a role for COL1A1 in the modulation of HCC CSCs-like phenotype." (PMID 31181620, 2019). "In addition, estrogen-induced increased expression of genes related to collagen synthesis, including COL14A1 and COL1A1 in mesenchymal cells, which was associated with cancer cell growth, invasion, metastasis, and angiogenesis." (PMID 39872660, 2024). "For example, the stromal subset consisted of endothelial cells identified by expressions of VWF, PECAM1 and KDR, pericytes with high RGS5, ACTA2, and COL4A1 expressions, and cancer-associated fibroblasts (CAFs) identified by significant expressions of COL1A1, DCN and LUM." (PMID 38925650, 2024). "Increased COL1A1 expression was associated with shorter overall survival, post-progression survival, and progression-free survival across the entire spectrum of cancer patients." (PMID 39034310, 2024). "The substantial overlap in metabolically regulated genes—such as IL6, IL1B, and COL1A1—in lung epithelial cells associated with PH and all published cancer analyses (where metabolites were elevated) suggests shared mechanisms linking transcriptional changes to genomic alterations." (PMID 39635438, 2024). "PDGFRA and COL1A1 were universally expressed in three commercially cancer associated fibroblasts." (PMID 39034310, 2024). "Interestingly, the staining levels of COL1A1, a significant component of cancer-associated collagens, and CD31, a representative endothelial cell marker, were reduced substantially in the LOXL4 KO cell-derived tumors and the LOXL4 mutCA subline-derived tumors." (PMID 37091157, 2023). "aberrant expression of COL1A1 is implicated in numerous cancers." (PMID 34698001, 2021). "COL1A1 is the α1 chain of type I collagen, and COL1A1 is aberrantly expressed in varieties of cancers, suggesting it may serve as an important diagnostic and prognostic marker and potential therapeutic target." (PMID 33564303, 2021). "In addition, we observed a strong positive correlation between COL1A1 expression and cancer-associated fibroblasts in most tumors." (PMID 34395525, 2021). "Moreover, genomic amplification of MMP13 and COL1A1 showed association with individual cancer stage." (PMID 33014334, 2020). "While aberrant expression of COL1A1 and COL1A2 is implicated in numerous cancers, the differential role of COL1A1 in malignant, premalignant and normal tissues remains unclear, and its clinical significance in HCC has not been elucidated." (PMID 31181620, 2019). "Thus, there may be a relationship among TGF‐β1, Runx2 and COL1A1 related to cancer cachexia‐associated SMF." (PMID 39091264, 2024). "The highest expression of genes encoding Col1a1-2, Col3a1, Col4a1, Col4a2, Col5a1, Col5a2, Col6a1, Col8a1, Col9a3, Col10a1, Col12a1, Col14a1, Col15a1, Col16a1, Col18a1, and Col28a1 were detected in untreated tumors, whose landscapes were dominated by Krt8+ cancer cells." (PMID 39372930, 2024).
cancer (continued). "Recently, the finding of collagen 1 α1–abundant (COL1A1-abundant) oncostreams and cancer-associated fibroblasts in GBM and their protumor effects reinforce the concept that components of the ECM might not be mere bystanders but could actively participate in the progression of GBM." (PMID 39207859, 2024). "Moreover, COL1A1 was closely associated with the overall survival of cancer patients." (PMID 34475986, 2021). "Furthermore, we presented the scatterplot of the correlation between COL1A1 expression with purity and the infiltration level of cancer associated fibroblast, CD 8+ T cells, and macrophages in certain types of tumors, and the scatterplot showed consistent results with the heatmap." (PMID 34395525, 2021). "In complete responders, skin lesion RNA sequencing after treatment, compared with baseline, identified increased inflammation (CXCL5, CXCL8, IL1A, COL1A1) and downregulated cancer markers (PRAME, S100B, MLANA, STK32A)." (PMID 42316430, 2026). "The PI3K-Akt signaling and proteoglycans in cancer were significantly enriched, involving proteins such as COL1A1, FN1, THBS1, FLNA, and ACTB." (PMID 40710368, 2025). "Our analysis revealed associations between the expression of COL1A1, ITGB1, THY1, and PDGFRA genes and different cancer stages in UCEC, however, the results were insignificant due to the lesser number of samples." (PMID 40817072, 2025). "Many hypoxia-upregulated genes, including COL1A1, COL5A1, COL6A3, LAMC2, and SERPINE1, are linked to enhanced migration, invasion, immune evasion, or treatment resistance in various cancers, including NSCLC." (PMID 41009714, 2025). "This study explores a novel approach to disrupt the expression of collagen by using adenine base editing to target Col1a1, a key gene driving both fibrosis and cancer metastasis." (PMID 40243657, 2025). "It has been stated that COL1A1 has a vital role in the metastasis of multiple types of cancer and the progression of other diseases." (PMID 38963646, 2025). "Immune-related genes, such as COL1A1, ITGB1, THY1, and PDGFRA, have been implicated in various cancers, but their roles in UCEC remain underexplored." (PMID 40817072, 2025). "We identified three major stromal cell types, including cancer-associated fibroblasts (CAFS; FAP, COL1A1), perivascular-like cells (PVL; PDGFRA, PDGFRB), and endothelial cells (PECAM1, CD34)." (PMID 40858992, 2025). "The ECM produced by COL1A1 can act as a physical barrier, thereby reducing drug penetration and providing cancer cells with protective signaling cues." (PMID 40282535, 2025). "In this study, treatment with Metformin was more effective than Pirfenidone or MitoQ in reducing both the levels of COL4A1 and COL1A1 as well as preventing a shift to glycolysis, typically occurring in cancer cells and pro-fibrotic myofibroblasts." (PMID 40104066, 2025). "In non-cancer models, COL1A1 knockdown increases reactive oxygen species (ROS) and disrupts mitochondrial membrane potential (ΔΨm)." (PMID 41040657, 2025). "The results indicated that, compared to adjacent non-cancerous tissues, the H-scores of CDK1, STAT1, COL1A2, and COL1A1 in cancer tissues were significantly elevated, with statistical significance (P < 0.05)." (PMID 39911265, 2025). "Other miRNAs, like miR-133a, can bind to collagen type I alpha 1 (Col1A1) to promote collagen accumulation, which in turn generates more attachment sites to facilitate cancer invasion." (PMID 40427172, 2025). "Shared pseudotemporally correlated genes between both integrated datasets included genes associated with proliferation (CENPF and TOP2A), cancer‐associated fibroblasts (DCN and COL1A1) and neurodevelopment (HMGB2 and NPAS3)." (PMID 39836549, 2025). "In cancer zone A, cancer cells primarily engaged in Col1a1/Col1a2-Itga9/Itgb and Fn1-Cd44 interactions to promote invasion and drive ECM remodeling." (PMID 40723284, 2025).
cancer (continued). "Surprisingly, SESN3 and COL1A1, which are downregulated in GATOR1 deletions, have pro-tumorigenic activity and their overexpression in cancer is associated with cisplatin resistance." (PMID 41469472, 2025). "The upregulated genes were associated with extracellular matrix remodeling and cancer pathways, including LAMC1-3, COL9A2, COL1A1, MYL9, MYH11, and KAT2A." (PMID 39735192, 2024). "COL1A1 is a gene, usually with heightened expression in multiple cancer types, that can potentially influence key cellular processes like cell proliferation, metastasis, apoptosis, and cisplatin resistance." (PMID 38392197, 2024). "Cancer-associated fibroblasts (CAF) expressed well-known markers including FAP, COL1A1, COL10A1, MMP11, and CTHRC120,21, and other genes such as INHBA, SLC12A8, F2R, and COL12A1 in various organs." (PMID 38744958, 2024). "We also showed that LC regulates Runx2 ubiquitination through DTX3L, leading to a decrease in COL1A1 and alleviating SMF caused by cancer cachexia." (PMID 39091264, 2024). "Collectively, these findings suggest that COL1A1 is dysregulated in multiple cancers, including OC, relative to matched normal tissues." (PMID 39845977, 2024). "In this study, we found that LC alleviates fibrosis through the DTX3L/Runx2/COL1A1 axis in our models of cancer cachexia." (PMID 39091264, 2024). "Type I collagen α1 (COL1A1) is a member of the collagen family that participates in epithelial-mesenchymal transition, which is closely related to malignant tumor development." (PMID 38441550, 2024). "Next, we analyzed COL1A1 mRNA expression across various cancers using the TNM plot database, which revealed that COL1A1 expression in OC tissues was significantly higher than in normal tissues." (PMID 39845977, 2024). "In the tissues of DGC patients, TINAGL1 was higher in cancer than paired normal tissues and detected with collagen type I alpha 1 chain (COL1A1) in the same spot." (PMID 38355577, 2024). "Earlier studies have also reported the association of COL1A1, COL1A2, COL3A1, and FN1 expression with OS in different other cancer patients." (PMID 38913913, 2024). "The results demonstrated that COL1A1 expression was significantly elevated in these cancer samples compared to normal tissues." (PMID 39845977, 2024). "The most marked cluster comprised of collagen genes associated with tissue remodelling (COL1A1, COL3A1 and COL6A3); these show steady increase in expression across normal, inflamed, dysplastic and cancer tissue." (PMID 38505585, 2024). "In metastatic LNs, most ligand‒receptor pairs are related to the collagen family, which includes genes such as COL1A1, COL1A2, and COL3A1, which are markers of cancer‐associated fibroblasts (CAFs)." (PMID 39312471, 2024). "EMT and fibroblast-myofibroblast-myofibroblast transition (FMT) are involved in the initiation and progression of cancer, and studies have demonstrated that fibroblasts with high levels of COL1A1 are related to EMT." (PMID 39712244, 2024). "To investigate the expression pattern of COL1A1 in cancer, we analyzed its expression levels using the GENT2 database." (PMID 39845977, 2024). "ER−/PR-cancers exhibited significantly (p < 0.0001) lower expression of COL1A1 and COL1A2 than ER+ tumors." (PMID 38102637, 2023). "Another particularly compelling example of a similarly misleading and likely artifactual fusion is COL1A1::FN1, which is detected as prevalent in cancer-associated fibroblast cell lines." (PMID 37323575, 2023). "In particular, we found that SDC1 was a key receptor mediating COL1A1+ CAFs and cancer cells, and it was significantly upregulated in both cell types." (PMID 37021816, 2023). "GeneVector reassigned a subset of cancer cells to fibroblast and the differentially expressed genes between these cells and the cells annotated as cancer by GeneVector highlighted fibroblast cell type markers including COL1A1." (PMID 37474509, 2023).